FOXP2 (forkhead box P2)
Diseases named in the same sentence as FOXP2 in open-access papers (continued):
Sharing a sentence is not in itself a finding about the gene and the disease.
multiple myeloma (6 papers, 2015 to 2022). "Our prior study of FOXP2 expression in cell lines derived from lymphoid malignancies detected expression primarily in multiple myeloma and Hodgkin's lymphoma." (PMID 27224915, 2016). "Western blotting and qRT-PCR across an extended panel of eleven DLBCL cell lines identified the ABC-DLBCL cell lines RIVA and SU-DHL-2 as also being strongly FOXP2-positive, with levels comparable to that in the myeloma cell line JJN3." (PMID 27224915, 2016). "The first, from our laboratory, described the high frequency expression of FOXP2 in malignant plasma cells in multiple myeloma." (PMID 27224915, 2016). "Given the expression of FOXP2 in myeloma and in the majority of ABC-DLBCL cell lines, we investigated whether it might be a potential marker of plasma cell differentiation in DLBCL." (PMID 27224915, 2016). "However, the ABC-DLBCL cell line OCI-Ly10 also showed comparable FOXP2 protein and transcript levels to those in myeloma and Hodgkin's lymphoma lines." (PMID 27224915, 2016). "Given a potential role for FOXP1 in development of bone osteoclasts and expression of FOXP2 in bone-resident myeloma cells (in which the bone niche has an essential role in disease pathogenesis and resistance to therapy), we considered whether FOXP2 might play an important role in bone biology." (PMID 26034982, 2015). "FOXP2 is expressed in the plasma cell malignancy multiple myeloma but has not been studied in DLBCL, where a poor prognosis activated B-cell (ABC)-like subtype display partially blocked plasma cell differentiation." (PMID 27224915, 2016). "This, and the expression of FOXP2 in MGUS and myeloma, raised the possibility that FOXP2, like FOXP1, might also be involved in DLBCL pathogenesis." (PMID 27224915, 2016). "Analysis of DLBCL cell lines initially suggested that FOXP2 expression was restricted to ABC-DLBCL, with only two of six cell lines studied here (RIVA and SU-DHL-2) and another (OCI-Ly10) from a previous study, exhibiting levels of nuclear protein expression comparable to the JJN3 myeloma cell line." (PMID 27224915, 2016). "Normal osteoblast development is compromised in bone metastases of solid tumours and in bone malignancies such as multiple myeloma, and thus characterisation of FOXP2 growth arrest function in a disease context may identify novel malignant pathways." (PMID 26034982, 2015). "FOXP2 being absent in normal B cells and most B-cell lymphoma cell lines while being expressed in a subpopulation of normal plasma cells and in plasma cell dyscrasias, such as monoclonal gammopathy of undetermined significance (MGUS) and myeloma." (PMID 27224915, 2016).
bipolar disorder (5 papers, 2015 to 2025). A disorder of the brain that causes unusual shifts in mood, energy, activity levels and the ability to carry out day-to-day tasks. "Finally, in a CNV mircroarray study of an extended bipolar disorder family with 5 affected relatives we previously identified a 131kb deletion in CNTNAP2 intron 1, removing a FOXP2 transcription factor binding site." (PMID 30586385, 2018).
depression (5 papers, 2020 to 2024). "As to LHX9, the hypothalamic marker has been proven highly correlated with FOXP2 in patients with depression." (PMID 36686487, 2022). "SPACOX identified multiple candidate loci for overall MD status, depression and SUD, such as rs139813674 (P value = 8.39 × 10–9, ZNF684) for overall MD status, rs7231178 (DCC, P value = 2.11 × 10–9) for depression, and rs10228494 (FOXP2, P value = 6.58 × 10–10) for SUD." (PMID 35017462, 2022). "The most significant novel pleiotropic locus (Index SNP: rs12705959, PCPASSOC = 4.95E-11) between depression and HEM was located near the intron of FOXP2." (PMID 39588545, 2024).
Obesity (5 papers, 2013 to 2025). Accumulation of substantial excess body fat. "Correlations between genes and weight loss were observed in two genes with known roles in obesity: FOXP2 (cg18546840 R = 0.85) and ACSL1 (cg00287477 R = 0.91)." (PMID 25651499, 2015). "Copy number variants in FOXP2 have been associated with childhood obesity and nominally associated with obesity in a familial case–control study." (PMID 25651499, 2015). "FOXP2 has also been associated with obesity in previous studies." (PMID 35992594, 2022). "In this context, changes in methylation at single CpGs within FOXP2 (cg26580413) were correlated with changes in weight (FOXP2, R = 0.85), and copy number variants in FOXP2 have been associated with childhood obesity and nominally associated with obesity in a familial case−control study." (PMID 41082226, 2025). "Additionally, FOXP2 has been associated with obesity in a genome-wide association study." (PMID 35992594, 2022). "Differential methylation is found within genes associated with obesity, epigenetic regulation and development, such as CETP, FOXP2, HDAC4, DNMT3B, KCNQ1 and HOX clusters." (PMID 25651499, 2015). "A role for FOXP2 in obesity is supported by the presence within the gene of independent SNP associations at P<10−3 with all of BMI, waist-hip ratio (adjusted for BMI) and insulin resistance." (PMID 23554873, 2013). "Furthermore, epigenetic analyses have revealed differential DNA methylation patterns of FOXP2 in adipose tissue of individuals with obesity." (PMID 41082226, 2025). "Differential methylation was found in genes associated with obesity, epigenetic regulation and development, such as cholesteryl ester transfer protein (CETP), forkhead box P2 (FOXP2), HDAC4, DNMT3B, potassium voltage-gated channel subfamily Q member 1 (KCNQ1) and homeobox (HOX) clusters." (PMID 36397166, 2022). "At least 4/15 genes containing ≥6 differentially methylated CpG sites had a potential role in obesity and/or related traits (PRKCZ, PRDM16, FOXP2, THBS1)." (PMID 25651499, 2015). "When we investigated the list of 162 DMRs mapping to annotated loci in further detail we observed other genes with known and potential roles in obesity and related traits (such as PRKCZ, NDUFS2, GATA2, FOXP2, ANGPT2, NCOR2, CPT1B, PTPN6)." (PMID 25651499, 2015).
diabetes (4 papers, 2020 to 2023). "Recent research has indicated FOXP2 is essential in mediating the proliferation and function of islet α cells, suggesting that FOXP2 might play a role in diabetes mellitus." (PMID 32183046, 2020).
cognitive disorder (3 papers, 2012 to 2021). A disease affects cognitive processes. "Disease-causing variants in both FOXP1 and FOXP2 are relatively rare, but play a significant role in the pathology of cognitive diseases." (PMID 22736078, 2012). "The phenotypic spectra of FOXP1 and FOXP2 disruptions suggest that these two closely related transcription factors are involved in both shared and distinct neurodevelopmental pathways underlying cognitive diseases through the regulation of common and exclusive targets." (PMID 22736078, 2012). "The findings discussed in this review show that FOXP1 and FOXP2 may provide crucial insight into the molecular pathways involved in human cognitive diseases." (PMID 22736078, 2012).
colorectal cancer (3 papers, 2020 to 2023). A primary or metastatic malignant neoplasm that affects the colon or rectum. "miR-9 also inhibits cell metastasis and EMT through targeting the forkhead box P2 (FOXP2) in colorectal carcinoma, and its downregulation is correlated with a poor prognosis." (PMID 32111074, 2020).
glioblastoma (3 papers, 2019 to 2021). The most malignant astrocytic tumor (WHO grade IV). "Aside from the downregulation in CCM patients, low levels of miR-181a-2-3p, which targets FOXP2, have been linked to a poorer prognosis in patients with glioblastoma, although the exact acting mechanism of FOXP2 in these malignant tumors remains unclear." (PMID 34199498, 2021). "Clinical features and relative expression of FOXP2 in glioblastoma (110 cases)." (PMID 31824836, 2019).
language delay (3 papers, 2012 to 2015). "These included genes associated with behaviorally important substances such as glucocorticoids, GABA, septin, calcineurin, as well as the genes CNTNAP2 (implicated in language delay in autistic children) and FOXP2 (known to be involved in vertebrate communication)." (PMID 23049809, 2012).
lung carcinoma (3 papers, 2022 to 2023). "In summary, EZH2 expression decouples from PRC2 activity, and a pattern of high EZH2, low H3K27me3 and high FOXP2 is enriched in poorly differentiated advanced lung cancers." (PMID 36670102, 2023). "A single study in lung cancer cells has shown that miR-671-3p enhances progression of lung cancer through blocking expression of FOXP2 expression in lung cancer, thus referring to an oncogenic role for this miRNA in lung cancer." (PMID 36545507, 2022). "Next, we tested whether the reduction of FOXP2 could reduce aggressive phenotypes of lung cancers." (PMID 36670102, 2023). "To extend our findings to human lung cancer patient samples, we performed immunohistochemical staining for EZH2, H3K27me3, and FOXP2 on lung cancer tissue microarray." (PMID 36670102, 2023). "Importantly, FOXP2 knockdown by shRNAs led to suppression of IL20RB in HBM1, indicating that IL20RB might be regulated by FOXP2 in lung cancer." (PMID 36006737, 2022).
Breast Invasive Carcinoma (2 papers, 2021 to 2022). "The levels of FOXP2 were significantly down-regulated in the group of invasive breast carcinomas compared to normal breast tissue." (PMID 33718155, 2021). "These fingerings indicated that FOXP2 and FOXP3 could be a promising biomarker to differentiate Breast Invasive Carcinoma tissues from normal tissues." (PMID 35614183, 2022).
cervical cancer (2 papers, 2019 to 2020). A primary or metastatic malignant neoplasm involving the cervix. "LncRNA MIR205HG can act as a ceRNA to promote the proliferation and migration of cervical cancer cells by reversing the inhibitory effect of miR-122-5p on FOXP2." (PMID 32025520, 2020). "MicroRNA-205 host gene (MIR205HG) has been found as a oncogene in cervical cancer by modulating miR-122-5p/FOXP2 axis." (PMID 31649871, 2019).
colitis (2 papers, 2022 to 2025). Inflammation of the colon. "Here, in our study, through performing RNA-sequence analysis of colitis-associated CRC constructed by AOM and DSS reagents, we found that FOXP2 was a potential target for preventing carcinogenesis." (PMID 35281860, 2022).
diffuse large B-cell lymphoma (2 papers, 2016 to 2023). "FOXP2 shares partially overlapping normal tissue expression and functionality with FOXP1; an established diffuse large B-cell lymphoma (DLBCL) oncogene and marker of poor prognosis." (PMID 27224915, 2016).
Hyperglycemia (2 papers, 2020 to 2022). An increased concentration of glucose in the blood. "A general increase in the levels of H2BS122OGlcNAc was seen in case of hyperglycemia compared with controls at all genes except Foxp2 at E14.5 and Ngn2 at E16.5." (PMID 35470239, 2022).
insomnia (2 papers, 2023). A sleep disorder characterized by difficulty in falling asleep and/or remaining asleep. "FOXP2 is a transcription factor that has been implicated in GWAS of insomnia, BMI, cannabis use disorder, and risk-taking, as well as short sleep duration." (PMID 37770476, 2023).
metastatic tumors (2 papers, 2015 to 2023). "Like-wise we observed a robust increase in RALYL and FOXP2 expression in metastatic tumors compared to the non-metastatic primary xenograft." (PMID 26159519, 2015).
microcephaly (2 papers, 2020). A congenital or acquired developmental disorder in which the circumference of the head is smaller than normal for the person's age and sex. "We observed one single m6A site near the stop codon in 7 microcephaly-related E-SMRs, including Brca2, Cep152, Ddx11, Nde1, Kif14, Stil and Cdk5rap2, 3 polymicrogyria-related E-SMRs (Eomes/Tbr2, Pax6 and Foxp2), and 3 megalencephaly-related E-SMRs (Gli3, Ccnd2 and Kif7)." (PMID 32992647, 2020).
non-small cell lung carcinoma (2 papers, 2015 to 2022). A group of at least three distinct histological types of lung cancer, including non-small cell squamous cell carcinoma, adenocarcinoma, and large cell carcinoma. "It was also stated that miR-671-3p regulates the proliferation, apoptosis, migration and invasion of non-small cell lung cancer cells by directly targeting FoXP2 (Forkhead box protein P2)." (PMID 35456388, 2022).
pancreatic carcinoma (2 papers, 2021 to 2023). "Our findings were consistent with previous data showing that the cell growth ability was decreased by Foxp2 knockdown in mouse pancreatic cancer cells." (PMID 37668356, 2023).
thyroid cancer (2 papers, 2022 to 2023). "As immune regulatory factor, the reduction of FOXP2 may affect tumor microenvironments and immune cells infiltration, enhance tumor immune escape, and promote recurrence of thyroid cancer." (PMID 36203616, 2022). "Lower FOXP1, FOXP2 and higher FOXP3, FOXP4 levels could be identified in thyroid cancer tissues when compared with matched normal tissue." (PMID 36203616, 2022).
triple-negative breast carcinoma (2 papers, 2020 to 2023). An invasive breast carcinoma which is negative for expression of estrogen receptor (ER), progesterone receptor (PR), and human epidermal growth factor receptor 2 (HER2). "The knockdown of FOXP2 attenuated the proliferation and invasion of triple-negative breast cancer, inhibited tumor progression, and metastasis." (PMID 32183046, 2020).
vitamin D deficiency (2 papers, 2016 to 2019). A nutritional condition produced by a deficiency of VITAMIN D in the diet, insufficient production of vitamin D in the skin, inadequate absorption of vitamin D from the diet, or abnormal conversion of vitamin D to its bioactive metabolites. "Vitamin D deficiency also reduces the amount of FOXP2-expressing cells in the developing cortex; FOXP2 is a key gene for language development and evolution." (PMID 30936846, 2019). "In a set of experiments examining the effect of maternal vitamin D deficiency on fetal brain development, Hawes and colleagues found that the pups from deficient mothers display a modulated expression of Bdnf, Foxp2, Tgfb1 and Th, which are also affected in certain conditions of our study." (PMID 26932723, 2016).
ADNP syndrome (1 paper, 2020). "Similarly, Foxp2 is implicated as critical for central control for normal bladder voiding behavior and may be important to tongue movement function, both affected in the ADNP syndrome." (PMID 32937737, 2020).
age-related macular degeneration (1 paper, 2022). Age-related loss of vision in the central portion of the retina (macula), secondary to retinal degeneration. "For instance, netrin-1-DCC signaling systems were associated with age-related macular degeneration and FOXP2 was associated with age-dependent dormant resident progenitors." (PMID 35017462, 2022).
asthma (1 paper, 2025). "Overexpression of Foxp2 in an asthma model inhibited Th9 differentiation and reduced IRF4 and BATF expression." (PMID 40909266, 2025).
benign prostatic hyperplasia (1 paper, 2023). A non-cancerous nodular enlargement of the prostate gland. "The amounts of FOXP2 protein were evidently increased in primary prostate adenocarcinomas relative to the matched normal tissues and benign prostatic hyperplasia (BPH) samples." (PMID 37668356, 2023). "(G) Left: representative images of FOXP2 protein expression in benign prostatic hyperplasia (BPH) (n = 25) or primary prostatic adenocarcinoma (PCA) (n = 45) by immunohistochemistry." (PMID 37668356, 2023). "Our findings revealed that FOXP2 protein expression is absent or low in normal human prostate epithelial cells and benign prostatic hyperplasia but is markedly increased in PIN, localized prostate tumors, and metastatic prostate cancer cell lines." (PMID 37668356, 2023).
cleft palate (1 paper, 2021). Cleft palate is a fissure type embryopathy that affects the soft and hard palate to varying degrees. "This comprehensive analysis revealed decreases in gene expressions associated with lung development; Foxa2, Notch1, Foxp2, Nkx2.1, and intestine development; Cdx2, Foxf2, Foxl1, and skeletal development; Hoxd12, Hoxd13, Scx, Brachyury, and cleft palate; Foxf2." (PMID 34671097, 2021).
cognitive decline (1 paper, 2024). "We hypothesize that the resilience of vocal learning to cognitive decline in open-ended learners will be reflected in an absence of age-related changes in neural FoxP2 expression." (PMID 38965498, 2024).
dementia (1 paper, 2024). Loss of intellectual abilities interfering with an individual's social and occupational functions. "FOXP2-rs17213159-C/T resulted associated with disease risk (OR = 2.16, P = 0.0004), as well as with age at onset and severity of dementia." (PMID 38828303, 2024).
Dysarthria (1 paper, 2013). Dysarthric speech is a general description referring to a neurological speech disorder characterized by poor articulation. "Behavioral findings in these studies support an emerging view that, in addition to the signature motor speech deficits of CAS and dysarthria, FOXP2 disruptions are associated with deficits in attentional, auditory-perceptual, sensorimotor, cognitive-linguistic and affective processes." (PMID 24083349, 2013).
endometriosis (1 paper, 2017). The growth of functional endometrial tissue in anatomic sites outside the uterine body. "Of these eight loci, three were associated with all endometriosis (LAMC3, CAPN14 and DEFA1), and six with Stage B disease (NAALADL2, NR2C1, C14orf132, FOXP2, CDH20 and LAMC3)." (PMID 28333195, 2017).
esophageal cancer (1 paper, 2019). A primary or metastatic malignant neoplasm involving the esophagus. "The immunohistochemistry results showed that the expression of FOXP2 in cytoplasm increased with the pathological grade, which was similar to the decreasing cytoplasmic expression of transcription factor ZEB1 in tumor tissues of patients with low grade esophageal cancer." (PMID 30728054, 2019).
frontotemporal dementia (1 paper, 2024). Frontotemporal dementia (FTD) comprises a group of neurodegenerative disorders, characterized by progressive changes in behavior, executive dysfunction and language impairment, as a result of degeneration of the medial prefrontal and frontoinsular cortices. "Some evidence suggests a possible link between FOXP2 genetic variability and frontotemporal dementia (FTD) pathology and related endophenotypes." (PMID 38828303, 2024).
glaucoma (1 paper, 2025). Increased pressure in the eyeball due to obstruction of the outflow of aqueous humor. "The broad developmental expression of FOXP4 and its role in anterior segment disease also warrant further studies exploring the links between other FOXP transcription factors, such as dimerization partners FOXP1 and FOXP2, in glaucoma and ASD." (PMID 40637512, 2025).
lung adenocarcinoma (1 paper, 2023). A carcinoma that arises from the lung and is characterized by the presence of malignant glandular epithelial cells. "Despite clues suggesting the importance of FOXP2 in maintaining stemness in lung epithelium, the roles it plays in lung adenocarcinoma have yet to be explored." (PMID 36670102, 2023). "To study the correlation of EZH2/FOXP2 expression with patient prognosis, we queried published RNA-sequencing data from The Cancer Genome Atlas using KM-Plotter39 on 366 lung adenocarcinoma samples." (PMID 36670102, 2023). "Taken together, these data indicate reduction in PRC2 activity confers sensitivity to BET inhibition and demethylase inhibition in lung adenocarcinoma, and FOXP2 could be a promising target of BET inhibition." (PMID 36670102, 2023).
malignant glioma (1 paper, 2019). A grade III or grade IV glioma arising from the central nervous system. "The results suggest that the expression level of FOXP2 is associated with SNHG1, and may be involved in the mechanism of SNHG1 on the biological behavior of malignant glioma cells." (PMID 30728054, 2019).